AHR (aryl hydrocarbon receptor)
Diseases named in the same sentence as AHR in open-access papers (continued):
Sharing a sentence is not in itself a finding about the gene and the disease.
Obesity (continued). "For example, in the present study, adipocyte AhR–deficient mice exposed to PCB-77 did not exhibit increased adiposity or body weight, suggesting that increased levels of the parent toxicant acted at AhR on other cell types to protect against obesity and impair glucose homeostasis." (PMID 25734695, 2015). "Correspondingly, CH223191, an AhR antagonist, has been shown to stimulate adipocyte differentiation in normal preadipcytes derived from human primary preadipcytes, and a natural occurring AhR agonist indole-3-carbinol possesses anti-obesity activities in high fat diet-induced obese mice." (PMID 25942489, 2015). "Importantly, under the same treatment, AhR KO mice appear resistant to obesity and its metabolic consequences." (PMID 24823865, 2014). "Collectively, these data suggest that drugs that target the AHR may be useful for treating cancer in human obesity." (PMID 24171117, 2013). "There have been hints that the AHR may be a participant in the regulation of fat metabolism and obesity." (PMID 22609946, 2012). "A large-scale epidemiological study to investigate a possible association between the human AHR and obesity has not been conducted." (PMID 22609946, 2012). "Interestingly, the expression of genes involved in low-grade inflammation associated with obesity such as COX-2 (cyclooxygenase 2), CTSS (cathepsin S), and MMP9 (matrix metalloproteinase-9), which are also AhR target genes, was elevated in obese patients." (PMID 21156398, 2011). "Therefore, it is reasonable to speculate that obesity induces a reduction in AhR signalling, which further prevents DETCs from rounding up and releasing cytokines upon activation." (PMID 39944225, 2025). "Furthermore, IPA supplementation in obese mice showed that it could effectively alleviate obesity and chronic inflammation, and the improvement effect may be related to the activation of AhR/IL-22 pathway to enhance intestinal barrier function." (PMID 40308638, 2025). "Furthermore, pollutants can induce obesity through the activation of AhR." (PMID 39825581, 2025). "Among the most frequently observed genes in metabolism-related processes, examples include AhR and LXR in AOPs associated with steatosis (e.g., AOP IDs 34, 57, 58 and 232), PPARα in AOPs describing lipid metabolism alterations (e.g., AOP ID 166), and ERα in an AOP related to obesity (AOP ID 493)." (PMID 38523647, 2024). "Indeed, intestinal inflammation increases during obesity and is negatively correlated with the expression of AhR and IL-22 genes, whereas treatment with AhR agonists restores the tight junctions of intestinal epithelial damaged by palm oil feeding and improves intestinal inflammation." (PMID 39200098, 2024). "Consequently, blocking the AhR pathway could improve the endothelial function in metabolic disorders such as obesity." (PMID 37686342, 2023). "Therefore, modulation of abnormal AhR activation could be a promising approach to prevent obesity and ameliorate neurodegenerative diseases." (PMID 36499198, 2022). "Interestingly, the implication of AhR in diet-induced obesity and NAFLD has also been described." (PMID 33477939, 2021). "Therefore, we would like to point out that commonly used models of diet-induced obesity may be confounded by alterations in intestinal AhR signaling, a problem that is even more pronounced when feeding of HFD is compared with NC rather than HFD ctrl." (PMID 32366032, 2020). "Furthermore, obesity factors including cholesterol and palmitic acid may interact with AHR signaling through the NLRP3 inflammasome and enhance the activation of markers of atherogenesis." (PMID 33167400, 2020). "Further studies, using additional tissue-specific and inducible knockout models, as well as determination of what AHR agonists are produced by high-fat diet will help to define how modulating AHR activities may be useful in prevention and therapeutic interventions for obesity and diabetes." (PMID 32730300, 2020).
Obesity (continued). "However, epidemiological studies have shown an association between various polymorphic forms of the AHR and cancer, but none have shown an association to obesity." (PMID 22609946, 2012). "Quercetin supplementation alleviates obesity by restoring high-fat diet induced gut microbiota disorder, which elevates IPA level to activate AhR/IL-22 pathway, thereby enhancing intestinal barrier integrity and suppressing chronic inflammation." (PMID 40308638, 2025). "Hepatic AhR activation increases circulating triglycerides and induces PAI-1 secretion, promoting inflammation and obesity." (PMID 40943373, 2025). "Peripheral blood transcript levels of AhR are significantly elevated in patients with familial hypercholesterolemia and T2DM, potentially promoting proinflammatory Th-cell differentiation in obesity and T2DM." (PMID 41440753, 2025). "AhR activation in the liver induces the endocrine hormone FGF21, which protects against obesity and insulin resistance, uncoupling hepatic steatosis from insulin resistance." (PMID 41440753, 2025). "Collectively, hyperglycemia or obesity impairs skin γδ T cell proliferation and function via STAT5, aryl hydrocarbon receptor (AHR) signaling, mTOR, the IL-15–IGF-1 loop, and other pathways." (PMID 41341586, 2025). "In male rats, the AhR is more active and induces SREBP-1C expression, leading to fatty liver, hypertriglyceridemia, and obesity." (PMID 39457607, 2024). "However, recent studies showed that the activation of AhR signaling with selective endogenous AhR ligands, particularly indole derivatives from gut microbiome, and novel endogenous ligands such as cinnabarinic acid, can protect against fatty liver disease and possibly obesity." (PMID 37284280, 2023). "Similar to α-naphthoflavone, the use of another AhR antagonist, CH223191 significantly reduced obesity and ameliorated hepatic steatosis in Western diet fed WT mice." (PMID 37284280, 2023). "In this study, we evaluated the anti-obesity and anti-inflammatory activity of HBU651, a novel AhR antagonist." (PMID 36499198, 2022). "Roles of AHR and NAD+-consuming enzymes in tissue-dependent inflammatory diseases have been discussed using two examples: infectious colitis and obesity-mediated NAFLD and NASH." (PMID 34559251, 2021). "The microbiota-derived indole-3-acetic acid is also an activator of the aryl hydrocarbon receptor (AHR), which, in addition, contributes to the protection against diet-induced obesity and intestinal barrier permeability." (PMID 35145486, 2021). "In this study, the relative amount of transcripts of the transcription factors AHR and RORC in PBMCs responsible for Th17 and Th22 differentiation were determined in obesity and T2D patients." (PMID 32849564, 2020). "Other authors, using the same mice strain, demonstrated that the inhibition of the AHR prevents the diet–induced obesity and fatty liver, suggesting that TCDD toxic/obesogenic effects can be avoided by blocking AHR." (PMID 30467492, 2018). "In addition, AhR deficiency may increase FAO and protect against HFD-induced obesity." (PMID 29375541, 2017). "In contrast to the AhR agonist Ficz, which improves glucose tolerance without affecting obesity, the administration of indole to high-density lipoprotein-fed mice can prevent obesity and impaired glucose tolerance." (PMID 39944642, 2025). "As evidenced by the numerous studies that IPA acts as an AhR ligand to increase IL-22 secretion, we hypothesized that quercetin improved obesity through influence in IPA production and activation of AhR/IL-22 axis." (PMID 40308638, 2025). "However, 5-HIAA derived from gut microbiota can improve glucose intolerance and obesity in HFD-fed mice, while preserving hepatic insulin sensitivity via directly activating AHR, which stimulates TSC2 transcription and thus inhibits mTORC1 signaling." (PMID 39426289, 2024). "Our results demonstrated that plasma AhR concentrations were significantly higher in men with obesity than in those without obesity." (PMID 37749614, 2023).
Obesity (continued). "Notably, kynurenine was shown to trigger obesity by binding to the aryl hydrocarbon receptor (AhR), and blocking IDO or AhR in mice significantly attenuated long-term high-fat diet-induced obesity and liver steatosis." (PMID 34473644, 2021). "In addition, the activation of AHR/CD36 pathway promotes hepatic steatosis in mice, while inhibiting the activity of AHR and altering the expression levels of CYP1B1, PPARα, and SCD-1 that attenuate the diet-induced obesity and hepatic steatosis in mice." (PMID 34722615, 2021). "Our data indicated that a general increase in expression of the AHR gene in PBMC not only correlated with the corresponding Th22 lineage, but also correlated with overall pro-inflammatory polarization of other Th subsets in obesity and T2D patients as well." (PMID 32849564, 2020). "Here, we used platelet-derived growth factor receptor alpha (Pdgfrα)-Cre mice, a Cre model previously established to knock out genes in preadipocyte lineages and other cell types, but not liver cells, to further define AHR’s role in obesity." (PMID 32730300, 2020). "Over-activation of AhR was shown to promote obesity, hepatic steatosis, nonalcoholic steatohepatitis, and insulin resistance." (PMID 33333918, 2020). "The AHR/ARNT heterodimer regulates the transcription of genes in the cytochrome P450 Cyp1 family and thousands of other genes including other nuclear receptors relevant to obesity." (PMID 32849564, 2020). "Moreover, unanticipated correlations among AHR transcripts and Th1 and Th17 cells were revealed in our further analysis, indicating that increased expressions of AHR gene may contribute to the overall pro-inflammatory polarization of Th lymphocytes in obesity and T2D patients." (PMID 32849564, 2020). "Although previous studies have indicated a role of AHR signaling in Th17 differentiation, there was no data showing its clinical relevancy with peripheral Th17 frequency in diabetes or obesity." (PMID 32849564, 2020). "In obesity, studies have demonstrated that AhR mediates DIO and its whole-body deletion in mice protects from diet-induced adiposity and metabolic disorders, while AhR has also been reported to have a protective role in HFD-induced hepatic steatosis." (PMID 30944419, 2019). "We identifed indigo, an aryl hydrocarbon receptor (AhR) ligand agonist, as a potent inducer of IL-10 and IL-22, which protects against high-fat diet (HFD)-induced insulin resistance and fatty liver disease in the diet-induced obesity model." (PMID 30944419, 2019). "More recent evidence suggests that gut microbiota, which can be modulated by the AHR, may play a pivotal role in POP-induced obesity." (PMID 25768209, 2015). "The intent of our study was to test more directly the role of the AHR in obesity and fat metabolism, but without exposure to exogenous toxicants." (PMID 22609946, 2012). "Studies have shown that the toxicant-activated aryl hydrocarbon receptor (AHR) may disrupt fat metabolism and contribute to obesity." (PMID 22609946, 2012). "Thus, we hypothesized that quercetin mitigated HFD-induced obesity through modulation of microbial metabolite IPA, which further activated AhR/IL-22 pathway to improve intestinal barrier function." (PMID 40308638, 2025). "Furthermore, the AhR inhibits AMPK activation, leading to obesity and liver steatosis." (PMID 39457607, 2024). "Therefore, we conducted a cross-sectional study to assess the EAT thickness and plasma AhR levels in men with and without obesity." (PMID 37749614, 2023). "Additionally, regulatory genes such as CD163, AHR, and CD52 were increased with pregravid obesity." (PMID 34195568, 2021). "However, to our knowledge, there was no study present concerning the expression of the AHR gene in patients with obesity or T2D." (PMID 32849564, 2020).
Obesity (continued). "Given that AHR may not be involved in Th1 polarization, it is quite possible that Th polarization in obesity and T2D may be regulated, at least partially, by expressions of AHR in other cell populations (e.g., monocyte) other than CD4+ T lymphocyte itself." (PMID 32849564, 2020). "Thus, new therapeutics that target AhR may improve HFD-induced intestinal barrier dysfunction, downstream inflammatory changes and overall obesity-related IR." (PMID 30944419, 2019). "However, at concentrations and doses previously shown to stimulate hormone secretion and reduce obesity-induced hyperglycaemia, the synthetic AhR agonist FICZ did not stimulate GLP-1 secretion from STC-1 cells, nor did it modify glucose tolerance in C57Bl6/J mice." (PMID 41776124, 2026). "With a significant positively correlation with serum hsCRP levels, AHR transcripts in PBMCs may represent as a novel mediator of the immune disturbance and meta-inflammation in obesity and T2D patients, independent of leptin, the previously-known key metabolic controller and immune modulator." (PMID 32849564, 2020). "The AhR agonists, such as environmental contaminants 2,3,7,8-tetrachlorodibenzo-p-dioxin (TCDD) and β-naphthoflavone (BNF), inhibit preadipocyte differentiation and interfere with the functions of adipose tissue, whereas the antagonist may have opposite or protective effects in obesity." (PMID 25942489, 2015). "Recent studies indicate that Burkholderia species carry out the microbial conversion of tryptophan into 5-HIAA via a non-traditional pathway, and then activates the AhR/TSC2/mTORC1 axis to improve glucose intolerance and obesity." (PMID 41273480, 2025). "However, the correlation between plasma AhR level and EAT thickness was not statistically significant in the obesity group (r = 0.202, P = 0.284) and in the control group (r = 0.157, P = 0.474)." (PMID 37749614, 2023). "Taken together, our data indicate that AHR, rather than ROR signaling, might have a more important role in the pro-inflammatory status in individuals with T2D and obesity." (PMID 32849564, 2020). "Together with the correlation analysis of Th lymphocyte polarization, our data indicate that AHR, rather than ROR signaling, might have closer ties with the pro-inflammatory status in T2D and obesity." (PMID 32849564, 2020). "Theoretically, increased peripheral Th22 and Th17 cells could be promoted both/either/neither by AHR and/or RORC signaling in T2D and/or obesity." (PMID 32849564, 2020). "In addition, as it was previously reported that a 30 % reduction in dietary TRP concentration induced thermogenesis without altering body composition in obesity-prone rats fed on HFD, we surmised that this could be due to diminished AHR activity." (PMID 40687891, 2025).
lung carcinoma (104 papers, 2004 to 2026). "Polycyclic aromatic hydrocarbons (PAHs), such as benzo[a]pyrene (B[a]P), are major risk factors for lung cancer and other diseases, acting through the aryl hydrocarbon receptor (AHR)." (PMID 42041582, 2026). "Kaplan-Meier survival curves showed that high AHR expression is associated with improved overall survival in lung cancer patients." (PMID 40303305, 2025). "AhR also has the ability to bind to the promoter regions of cMyc, a gene implicated in various stages of lung cancer development, notably in drug resistance." (PMID 39578555, 2025). "Among patients treated with pembrolizumab in a lung cancer cohort, high AhR expression was associated with partial response or stable disease, whereas low AhR expression was associated with disease progression." (PMID 38339226, 2024). "Accordingly, AhR has been reported to suppress some lung cancers, including those with KRAS-driver mutations characteristic of PAH-induced genotoxicity and smoking." (PMID 37696458, 2023). "For lung cancer, as for many other cancer types, AhR has been implicated at all stages of tumor development including initiation, promotion, progression, invasion, and metastasis." (PMID 37696458, 2023). "Clarifying the underlying mechanisms for this “Janus-faced” role of AhR in lung cancer will be important." (PMID 37696458, 2023). "Altogether, these elements reveal the interest and the complexity of miRNAs in air pollution-induced lung cancers and underline the need to further explore biological importance of the AhR in miRNA-induced processes, notably in link with EVs." (PMID 37696458, 2023). "AhR overexpression was associated with upregulation of IL-6 secretion, which is critical for lung cancer initiation." (PMID 35101137, 2022). "As an example, in lung cancer, a high AhR-associated genetic signature is associated with an unfavorable prognostic, implying the need to use antagonists." (PMID 35681770, 2022). "Although predictability is poor, AhR/Wnt-variants are unexpectedly overrepresented in optimized prediction scores for overall lung cancer and for small cell lung cancer." (PMID 35101137, 2022). "Complex interaction patterns of genes assigned to AhR/Wnt-signalling were recently associated with lung cancer susceptibility." (PMID 35101137, 2022). "Overall, these results implicated the therapeutic potential of AhR inhibitors in EGFR-associated lung cancer." (PMID 35831824, 2022). "AHRR, an Aryl hydrocarbon receptor repressor, a known tumor suppressor has been associated with smokers in lung cancer patients in an epigenetic manner." (PMID 34796107, 2021). "The previous studies found that the combination (multiple-variant haplotype) of multiple AhR polymorphisms contributed to the susceptibility of lung cancer." (PMID 33278884, 2020). "We found that a lower basal level of AhR was associated with high cell motility in lung cancer cells." (PMID 28195146, 2017). "Similarly, the AhRL benzo(a)pyrene (BaP) induced PD-L1 expression on lung epithelial cells and promoted lung cancer progression, while anti-PD-L1 antibodies or AhR deficiency suppressed BaP-induced lung cancer progression." (PMID 38339226, 2024). "The loss of AHR expression in human lung cancer tissues as demonstrated in this report supports such a hypothesis." (PMID 37151890, 2023). "Clarifying the role of AhR in lung cancer development associated with air pollution and combustion PM may provide tools for detecting vulnerable populations and give a deeper understanding of essential risk factors." (PMID 37696458, 2023). "Therefore, future research needs to dissect the potential molecular functions of PLK1 and AHR in these less explored lung cancer variants." (PMID 37988371, 2023).